OLA1 (Obg like ATPase 1)
Diseases named in the same sentence as OLA1 in open-access papers (continued):
Sharing a sentence is not in itself a finding about the gene and the disease.
tumor (16 papers, 2015 to 2025). "In various clinical subgroup analyses of tumor-associated autoantibodies, many findings are largely consistent with our research results on anti-OLA1 autoantibody." (PMID 41246329, 2025). "An analysis of the diagnostic efficacy of anti-OLA1 autoantibody was conducted across different clinical subgroups, including metastasis status, tumor multiplicity, TNM stage, gender, and AFP status, due to the limited sample size in the Beijing center, data from the other two centers were used." (PMID 41246329, 2025). "Interestingly, in the same cohort, lower OLA1 mRNA expression is associated with an increased depth of tumor invasion (p = 0.021) or metastasis (p = 0.051) in 1215 patients." (PMID 26283179, 2015). "Tumors were established on 12 days after implantation, as evidenced by the fact that OLA1-KO cells developed much more slowly than control cells, and tumor sizes in these mice were significantly less than those in control mice." (PMID 35440019, 2022). "The results demonstrated tumor tissue samples had a considerable up-regulation of OLA1 in these datasets." (PMID 35440019, 2022). "Clinical progression and prognosis of these tumours is influenced by the cellular Ola1 concentrations." (PMID 35056463, 2021). "As expected, marked OLA1 levels were observed in CRC tissues compared with those in matched tumor-adjacent controls, which exhibited the properties of an oncogenic gene." (PMID 34743750, 2021). "Overexpressed OLA1 plays essential roles in various bioprocesses and pathogeneses such as autophagy in the tumor cell–matrix mitochondria, oxidative stress, and release of ketones, lactic acid, and glutamine." (PMID 34743750, 2021). "Furtherly, UM-2 shOLA1 siR-SMAD2 cells were constructed to study the role of SMAD2 in OLA1 involvement in tumor migration." (PMID 32928102, 2020). "We first analyzed OLA1 expression profile across all tumor samples and paired normal tissues in the RNA sequencing data from Gene Expression Profiling Interactive Analysis (GEPIA)." (PMID 32528278, 2020). "Real-time PCR analysis of 20 pairs of fresh tumor tissues and normal liver tissues demonstrated that OLA1 was upregulated in HCC tissues (p<0.01)." (PMID 32045367, 2020). "Among all 32 putative target genes of miR-193a-5p, we identified four tumor-associated genes, including CUX1, ITSN1, OLA1, and RAP2A." (PMID 33014778, 2020). "OLA1 expression was positively correlated with tumor size (p<0.01), PVTT (p<0.01), TNM stage (p=0.01) and tumor differentiation degree (p<0.01)." (PMID 32045367, 2020). "Currently, literature reports that OLA1 was involved in EMT transformation in different tumor cells." (PMID 32528278, 2020). "IHC analysis showed that OLA1 expression was lower in normal lung tissues than in paired tumor tissues, and low-expression OLA1 was mainly localized in the cytoplasm of the bronchial and alveolar epithelium (data not shown)." (PMID 26863455, 2016). "We then performed several xenograft experiments to investigate the role of OLA1 in tumor growth in vivo." (PMID 26283179, 2015). "We compared OLA1 expression with clinical parameters including patients’ age, tumor size, histological type, pT (tumor invasion stage), and pN (LN metastasis) by ANOVA analysis, without finding a significant correlation." (PMID 26283179, 2015). "This discovery suggests that OLA1 may play an important role in regulating immune responses within the HCC tumor microenvironment, potentially resulting in alterations of autoantibodies against this protein in the serum." (PMID 41246329, 2025). "Mechanistically, GSEA showed that OLA1 might promote tumor progression by regulating the cell cycle and apoptosis." (PMID 32045367, 2020). "To detect whether OLA1 expression levels affected tumor progression in vivo, we constructed stable OLA1-knockout LM3 and MHCC-97H cells using lentiviruses carrying shRNA." (PMID 32045367, 2020).
tumor (continued). "This article also investigated whether the OLA1 medicated EMT process leading to tumor metastasis is related to tumor drug resistance." (PMID 32928102, 2020). "Finally, we analyzed SKOV3 xenograft tumor tissues and found that in 3 of 4 pairs PP1 was more active in the OLA1-KD tumor than the CTL tumor." (PMID 26655089, 2016). "Interestingly, in the harvested OLA1-KD tumor tissues, we also observed over-activation of GSK3β, as reflected by decreased GSK3β phosphorylation at Ser-9 (GSK3β-p) and diminished expression of Snail, a downstream target of GSK3β." (PMID 26655089, 2016). "Together, they provide a more comprehensive explanation, at the cell-signaling level, for the phenotypes demonstrated in OLA1-KD cells, including increased resistance to multiple cellular stresses, accelerated adhesion, decreased cell migration, and decreased apoptosis during tumor growth in vivo." (PMID 26655089, 2016). "OLA1 is also highly expressed in various tumor types including CRC, and the expressions of OLA1 and ZFAS1 in CRC tissues are highly consistent." (PMID 34743750, 2021). "Collectively, in vivo experiments demonstrated that IMP2 knockdown inhibits the tumor growth and prognosis of the xenografts via the interaction of IMP2 with the ZFAS1/OLA1 axis through m6A-induced stability in CRC." (PMID 34743750, 2021). "In this article, we reported that OLA1 participates in the EMT process through the TGFβ/SMAD axis, which in turn affects tumor metastasis." (PMID 32928102, 2020). "To further investigate the OLA1 expression in OSCC, we analyzed gene expression omnibus (GEO) Datasets (GSE140707) with three tumorous and adjacent tissues from OSCC sufferers and found that OLA1 mRNA was downregulated in tumors." (PMID 32928102, 2020). "Moreover, several published studies have designated p.Thr716Ala as deleterious, arguing that it abolishes binding to OLA1, a protein interacting in BRCA1-BARD1 complex, leading to the alteration of BARD1 tumor suppressor activity." (PMID 35595798, 2022). "However, the higher OLA1 copy numbers were identified in all stages of CRC and were unconnected with tumor stage." (PMID 35440019, 2022). "Similarly, an elevated OLA1 level was further confirmed in paired CRC tissues and compared with that of the matched tumor-adjacent controls (n = 5) using qPCR assays." (PMID 34743750, 2021). "Our interpretation is that the advanced tumor growth under OLA1-KD is not due to a change in cell proliferation, but a result of decreased apoptosis in response to intratumoral stresses, associated with attenuated ISR and reduced expression of CHOP." (PMID 26655089, 2016). "By regulating TC formation, and other cellular processes to be further characterized, OLA1 participates in ISR and cell fate decisions in stressed cells, impacting the outcome of stress response in general and specifically, the overall growth and progression of a tumor." (PMID 26283179, 2015). "Currently we are not clear about the role of OLA1 in tumorigenesis, nor could our data rule out the requirement of OLA1 in in vitro growth and early-phase tumor growth." (PMID 26283179, 2015).
heart diseases (1 paper, 2024). "We believe this PCR-based assay will be highly useful to noninvasively screen for risks of developing heart disease due to a mutation in OLA1 using easily accessible cells or tissues, such as blood cells." (PMID 38889130, 2024). "Future studies with larger sample sizes will have to consider these confounding factors to provide a more comprehensive understanding of the relationship between OLA1 mutations and heart disease." (PMID 38889130, 2024). "To investigate the presence of mutations in the OLA1 gene associated with heart disease, we performed amplification of the OLA1 gene encompassing all exons as well as portions of the adjacent introns from DNA isolated from failing (n = 5) and non-failing (n = 5) human heart tissues." (PMID 38889130, 2024). "Our study also identified the same mutation in the OLA1 gene among patients with heart disease." (PMID 38889130, 2024). "Additionally, the presence of several mutations in the intronic regions of OLA1 suggests a potential RNA splicing defect contributing to OLA1 misregulation in heart disease, and warrants further exploration." (PMID 38889130, 2024). "Given the importance of OLA1 in heart diseases, we characterized OLA1 at both mRNA and genomic levels and compared it with other species." (PMID 38889130, 2024).
OLA1 also shares sentences with these, for which no sentence is quoted: pancreatic cancer (2 papers); carcinoma in situ (1); cholangitis (1); COVID-19 (1); endometrial cancer (1); gastric cancer (1); head and neck squamous cell carcinoma (1); Jaundice (1); lung squamous cell carcinoma (1); nasopharyngeal carcinoma (1); Optic neuropathy (1); triple-negative breast carcinoma (1).